INS (insulin)
Diseases named in the same sentence as INS in open-access papers (continued):
Sharing a sentence is not in itself a finding about the gene and the disease.
Hyperinsulinemia (continued). "For women, IR and hyperinsulinemia lower Sex Hormone-Binding Globulin levels, increasing free sex hormones, while IGF-1 interacts with insulin signaling and hormone receptors, collectively promoting the development of hormone-sensitive tumors in women, such as breast and endometrial cancer." (PMID 41419984, 2025). "Hyperinsulinemia, positive insulin antibodies, and fluctuations in glycemic levels without the use of insulin are hallmarks of IAS." (PMID 41234224, 2025). "In contrast to glucose or hemoglobin A1c, fasting insulin is not routinely measured in the clinic, but hyperinsulinemia can occur years before glucose is chronically elevated." (PMID 41178720, 2025). "‐ Decreased insulin levels at fasting and 30 mins postprandial (p = 0.005 for males, actual values not available) with increased glucose/insulin ratios suggesting decline in hyperinsulinemia prevalence." (PMID 40065629, 2025). "Both insulin and beta amyloid are degraded by the insulin-degrading enzyme (IDE); thus, hyperinsulinemia present in DM patients may competitively affect the increase in beta amyloid accumulation." (PMID 41295439, 2025). "It has been demonstrated that fasting insulin and the prevalence of hyperinsulinemia have increased remarkably among nondiabetic US adults." (PMID 40365140, 2025). "Although Ide is thought to participate in the clearance of extra- and intracellular insulin, Ide−/− mice display only mild or no hyperinsulinemia, suggesting a complex role of Ide in insulin clearance." (PMID 40497968, 2025). "In addition, we observed an increase in insulin levels in the HFD + STZ mouse model group compared to the normal group, indicating the presence of hyperinsulinemia." (PMID 40136402, 2025). "Since hyperinsulinemia is considered a potential contributor to DCM, it is noteworthy that STZ injection, which induces pancreatic damage, led to a significant reduction in insulin levels, resulting in hypoinsulinemia in this model." (PMID 40279648, 2025). "In the six equids with hyperinsulinemia and laminitis, insulin concentration (median, 618 pmol/L; IQR, 545–2153) was not different (p = 0.33) than in the six hyperinsulinemic horses without laminitis (median, 686 pmol/L; IQR, 472–919)." (PMID 40317948, 2025). "The presence of endogenous hyperinsulinism in the absence of serum secretagogue metabolites and insulin antibodies should raise the suspicion of insulinoma." (PMID 40161293, 2025). "This long-term detrimental effect on beta-cell function explains why elevated cholesterol results in decreased insulin secretion rather than hyperinsulinism in more advanced stages of the disease." (PMID 40137942, 2025). "The fact that the efferent VNS restored the hyperinsulinemia only partially indicated the synergistic effect of inflammation on the disruption of glucose–insulin homeostasis when vagal control is absent or diminished." (PMID 38248469, 2024). "Hyperinsulinemia also increases Aβ deposition as well as neurofibrillary tangles (NFTs) formation, and also have a negative impact on insulin signaling." (PMID 39518747, 2024). "A previous study by Li et al24 found that the prevalence of hyperinsulinemia increased by 35.1%, and the mean fasting insulin concentrations increased by 5% among nondiabetic US adults from 1988 to 2002." (PMID 39606490, 2024). "Although hyperinsulinemia can occur in the absence of tissue IR, it is well-known that decreased peripheral insulin sensitivity is a major culprit for compensatory insulin release." (PMID 39682351, 2024). "Neither do our findings indicate that insulin per se, at least at physiological levels, potentiates accumulation of total RNA through p70S6K stimulation as observed with hyperinsulinemia in human skeletal muscle." (PMID 38459192, 2024).
Hyperinsulinemia (continued). "In contrast, there is evidence showing that during IR, the mitogenic pathway activated by insulin, responsible for cell proliferation stimulation and apoptosis inhibition, is not affected and possibly upregulated by hyperinsulinemia." (PMID 39408212, 2024). "Hyperinsulinemia because of insulin overproduction leads to increased binding of insulin to the IR and to the non-preferred IR/IGFR complexes, which leads to an excessive and uncontrolled influence on growth, proliferation, and differentiation." (PMID 39123454, 2024). "Thus, the relationship between insulin and IGFBP-I is inverse, where IGFBP-1 is low during states of hyperinsulinemia but elevated during states of hypoinsulinemia." (PMID 39665021, 2024). "Hyperinsulinemia occurs when the organs become insulin-resistant and do not recognize the insulin response to glucose uptake." (PMID 39064681, 2024). "In a study published about ten years ago and performed on 328 patients with type 2 diabetes, it was shown that patients with higher levels of circulating insulin had worse cognitive function than those without hyperinsulinemia." (PMID 39061991, 2024). "Thirdly, women with a prior history of GDM, who have decreased insulin sensitivity and increased insulin secretion, may be more prone to developing NAFLD due to compensatory hyperinsulinemia, as insulin is known to stimulate hepatic lipogenesis." (PMID 38504196, 2024). "We found a widespread rise in hyperinsulinemia and IR prevalence and fasting insulin concentrations among nondiabetic adults in the US from 1999 to 2018." (PMID 39606490, 2024). "Hyperinsulinemia, which could take place in people affected by T1DM mellitus due to exogenous insulin administration, could affect this mechanism by interfering with lipolysis and fat oxidation." (PMID 38542818, 2024). "There is also a reciprocal relationship between insulin and the SNS: hyperinsulinemia leads to a sustained increase in basal SNS tone via effects on the brain, while chronically elevated SNS tone exacerbates IR and hyperinsulinemia." (PMID 39012663, 2024). "The absence of hyperinsulinemia and the finding of increased pAKT levels in the adipose tissue suggest that these mice have improved adipose tissue insulin sensitivity." (PMID 39283743, 2024). "Circulating FFA and FABP levels were not significantly higher in WC groups, suggesting hyperinsulinemia and hypersecretion of insulin are mediated through alternate pathways." (PMID 38961153, 2024). "In L-SACC1 mice, hyperinsulinemia results from impaired hepatic insulin clearance rather than a primary defect in insulin signaling or response to increased visceral obesity." (PMID 40808720, 2024). "Most previous antidiabetic drugs induce insulin directly or indirectly, while SGLT2-I does not cause hyperinsulinemia." (PMID 38304078, 2024). "The fasting plasma insulin level of the SFN group was approximately 40% lower than that of the HFD group, suggesting short-term intervention with SFN may ameliorate hyperinsulinemia condition in diabetic mice." (PMID 38611359, 2024). "In the case of insulin, hypoinsulinemia and hyperinsulinemia are “poisons”, whereas normoinsulinemia is not “poison”." (PMID 38397072, 2024). "The complexes did not potentiate the transport of [14C]-deoxy-D-glucose to hyperinsulinemia-induced insulin-resistant hepatocytes at 10 μM, nor did metformin at 1 mM." (PMID 38399444, 2024). "Furthermore, our findings underscore the pivotal role of hyperinsulinism in PBH aetiology, emphasizing the significance of the BA-GLP-1-insulin axis." (PMID 38842763, 2024). "Additionally, our research reinforces the role of hyperinsulinism as being the main mechanism of PBH and also the importance of the BA-GLP1-insulin axis." (PMID 38842763, 2024).
Hyperinsulinemia (continued). "Regarding the response to insulin of individual amino acids, the net leg balance of tyrosine (a non-essential amino acid) was not affected by hyperinsulinemia at all, whereas that of BCAAs and methionine was switched from net release towards net uptake." (PMID 38201949, 2023). "In addition, hyperinsulinemia is common in people with T2DM, and insulin also affects the release of TRH and TSH." (PMID 37484968, 2023). "Given that insulin is a primary regulator of CREB and FOXO transcriptional activity, we speculated that hyperinsulinemia induced by CORT is a major factor contributing to systemic metabolic changes." (PMID 36917179, 2023). "Hyperinsulinemia can drive hepatic lipogenesis and lipid accumulation directly as well as through indirect mechanisms, including excess circulating FFA, that impede the ability of insulin to inhibit hepatic glucose production." (PMID 37056675, 2023). "Comparisons of clinical characteristics between insulin-treated type 2 subjects with hyperinsulinemia with and without IAs." (PMID 37324170, 2023). "Hyperinsulinemia occurs when blood sugar levels rise, insulin action in the body is not carried out, and insulin resistance does not manifest as a result of impaired insulin function." (PMID 37623224, 2023). "Second, acute insulin stimulation following hyperinsulinemia reduces, but does not eliminate, insulin receptor activity." (PMID 37834116, 2023). "Additionally, contrast to previous findings that insulin significantly suppresses IGFBP-1, our results suggested that the suppression of PCOS-related hyperinsulinemia on IGFBP-1 seemed diminished." (PMID 38174331, 2023). "When ligand/receptors are constantly exposed to insulin, a negative feedback loop down regulates insulin receptor availability to insulin, creating a relative hyperinsulinemia." (PMID 37446104, 2023). "Another biological link is hyperinsulinemia, a condition that occurs due to the body's resistance to the effects of insulin in the blood and the pancreas attempts to compensate for the lack of insulin by producing increasingly more insulin." (PMID 36533539, 2023). "Similar to the Ra glycerol, hyperinsulinemia did not suppress NEFA levels of IRΔWB mice These results support the notion that brain insulin signaling is a key determinant of WAT function in mice regulating lipolysis even in the absence of peripheral IR." (PMID 37100238, 2023). "Hyperinsulinemia in portal vein leads to enhanced responsiveness of liver GH receptors and IGF-1 production, pointing towards a mutually amplifying loop between GH-IGF-1 axis and insulin." (PMID 36882643, 2023). "Concerning this phosphorylation, it has also been reported that hyperinsulinemia may result in the permanent phosphorylation of IRS-1 on Ser307, resulting also in the hampering of insulin signaling." (PMID 38247463, 2023). "Furthermore, this elevation of insulin concentrations was maintained throughout the test when compared to CTL, suggesting a picture of persistent hyperinsulinemia." (PMID 36902158, 2023). "Insofar EMS horses are characterized by persistent insulin desensitization, the consequent hyperinsulinemia exerts a negative feedback that strongly inhibits autophagic pathways." (PMID 37020593, 2023). "17α-E2 treatment also only improved hyperinsulinemia and insulin sensitivity in female WT, and not ERβKO, mice." (PMID 37330610, 2023). "Studies have demonstrated that higher insulin signaling in the long term (chronic hyperinsulinemia) does not inhibit but rather stimulates hepatic VLDL1-TAG synthesis and secretion, even when NEFA levels are lowered." (PMID 37404855, 2023). "The ovary does not develop IR and remains sensitive to the high levels of insulin that occur in IR and hyperinsulinemia." (PMID 37109585, 2023).
Hyperinsulinemia (continued). "The lack of hyperinsulinemia (a marker of pancreatic beta cell function) or impaired WAT insulin signaling suggests that the hepatic impairment of insulin signaling precedes extra-hepatic manifestations of glucose dysregulation in early SMAFLD." (PMID 37134024, 2023). "Moreover, because hyperinsulinemia is one of the major features of PCOS, the authors selected treated GCs with insulin to construct a PCOS model." (PMID 37562217, 2023). "However, very little peripheral insulin can access the brain, because its capability of passing the BBB is greatly weakened by hyperinsulinemia and brain insulin resistance in T2D through the selective and saturated transport of capillary endothelial cells." (PMID 37667187, 2023). "Patients with a primary insulin secretion defect without impairment of insulin sensitivity and patients with a primary insulin sensitivity defect with hyperinsulinemia can be distinguished." (PMID 36983056, 2023). "Theoretically, metformin and other insulin sensitizers reduce hyperandrogenism and hyperinsulinemia in patients with PCOS and revert the ovulatory cycle to normal." (PMID 38406771, 2023). "FFC-EtOH impairs glucose tolerance without concomitant hyperinsulinemia more than either dietary component alone, a consequence of both dysregulated hepatic insulin signaling and carbohydrate metabolism." (PMID 37134024, 2023). "In contrast, genetic deletion of Mboat7 in hepatocytes is sufficient to drive hepatic steatosis but does not drastically alter hyperinsulinemia or insulin sensitivity in either chow or HFD fed mice." (PMID 36806709, 2023). "As postmortem brains from late stage AD patients indicate hyperinsulinemia and altered insulin signaling, determination of the impact of AU9 on brain glucose uptake and insulin signaling will help us better understand the impact of PPAR signaling on brain energy regulation." (PMID 37190025, 2023). "Severe hypoketotic hypoglycaemia mimicking hyperinsulinism but without detectable insulin has recently been described in syndromic individuals with mosaic genetic activation of post-receptor insulin signalling." (PMID 37974153, 2023). "There was a strong relationship between insulin and SHBG, and SHBG could be a marker for either hyperinsulinemia, IR, or both, in obese children (aged 6–9 years)." (PMID 35684072, 2022). "The lack of insulin pulses decreases hepatic clearance of insulin leading to peripheral hyperinsulinemia." (PMID 35163806, 2022). "As hyperinsulinemia decreases IGF-binding protein–1 (IGFBP-1) and IGFBP-2 levels, insulin may reduce certain IGFBP levels and increase bioavailable IGF levels to indirectly enhance the IGF–IGF-1R signaling pathway." (PMID 36213272, 2022). "Moreover, significantly increased insulin level was found in both serum and CSF in HFD feeding mice, suggesting prolonged HFD led to IR characterized by hyperinsulinemia and glucose metabolic disorders." (PMID 36466168, 2022). "One hypothesis may be that, in states of hyperinsulinemia, such as DM2 and being on an insulin pump, excess insulin signaling can be cytotoxic to cardiomyocytes, as is demonstrated by the dose-response curve in our in vitro studies." (PMID 35574440, 2022). "Plasma insulin levels were significantly increased in HFD-fed Mkp-2−/− mice compared with Mkp-2+/+ mice, suggesting that Mkp-2−/− mice exhibit physiological hyperinsulinemia." (PMID 35745205, 2022). "Hyperinsulinemia is diagnosed using the OGTT and is based on insulin sensitivity index values." (PMID 35628058, 2022). "More evidence supports that initial increase of insulin secretion by CX3CL1/CX3CR1 may be just a defensive reaction to inflammation, which can lead to chronic hyperinsulinemia and depletion of functional reserves of β-cells." (PMID 35370759, 2022). "Olanzapine resulted in hyperinsulinemia and reduced insulin sensitivity during an OGTT at day 19, changes not observed with OLZ/SAM or placebo." (PMID 34887529, 2022).
Hyperinsulinemia (continued). "In our study, empagliflozin markedly reduced hyperinsulinemia, although no significant changes in insulin sensitivity were observed in muscle and adipose tissue, as well as in fasting or non-fasting glucose levels." (PMID 36140169, 2022). "Regardless of the mechanism of action, our current results demonstrate that postprandial hyperinsulinemia may be reduced using a synthetic GLP-1 agonist and this may be useful for the therapy of insulin dysregulation in horses with ID." (PMID 35906619, 2022). "Fasting insulin levels showed an increase of 2.006 ng/mL (p < 0.05) in the HSD group at 8 weeks of the experiment when compared with 4 weeks in the STD group, suggesting that rats fed the HSD for 8 weeks had hyperinsulinemia." (PMID 36079722, 2022). "When a delayed and blunted insulin response happens in PDA patients, elevated blood glucose levels then stimulate insulin synthesis and secretion in pancreatic islet beta cells, leading to endogenous hyperinsulinemia." (PMID 35252207, 2022). "Plasma insulin levels were not measured in high-dose exposure models, but two studies reported hyperinsulinemia following low-dose Aroclor exposure and then fasting hypoinsulinemia after recovery and subsequent reexposure to Aroclor." (PMID 35156417, 2022). "In summary, results from our studies suggest that in mice subject to euglycemic hyperinsulinemia for 5–120 min, insulin does not exert a significant effect on cardiac function." (PMID 36073057, 2022). "Nevertheless, due to concern for possible exacerbation of hyperinsulinemia with exenatide administration (since it is generally used as an insulin secretagogue) horses with severe ID were not specifically recruited for this study." (PMID 35906619, 2022). "The rate of glucose infusion required to maintain euglycemia during hyperinsulinemia (M-value) was also unchanged (7.7 ± 3.8 vs. 8.5 ± 4.7 mg/kg/min, air vs. AIH, p = 0.10) after correcting for plasma insulin levels (M/I-value) (8.7 ± 3.9 vs. 9.2 ± 5.0 mg/kg/min/μU/ml, air vs. AIH, p = 0.54)." (PMID 35313531, 2022). "The progression of these abnormalities leads to hyperinsulinemia in an effort of pancreatic β-cells to provide the required insulin, which is not reaching cells because of a dysfunction in the insulin receptor signaling pathway." (PMID 36233611, 2022). "Hyperinsulinemia increased CRH, ACTH and corticosterone in rats and a similar increase in ACTH and cortisol was observed in healthy, lean men in response to acute supraphysiologic insulin infusion." (PMID 35544473, 2022). "Without infusing a large amount of exogenous insulin to establish hyperinsulinemia, different extents of C-peptide reduction, such as >30%, 35%, approximately 40%, >50% were reported." (PMID 35935883, 2022). "This insulin-inducing effect on CCND1 in DOX-treated cells was also confirmed by immunostaining and provide additional support to the notion that chronic hyperinsulinemia aggravates hepatocyte senescence acting through insulin-activated cell cycle dynamics." (PMID 35872305, 2022). "There is also preclinical evidence that hyperinsulinemia can lead to partial reactivation of PI3K signaling; hence, administering insulin may theoretically interfere with the therapeutic activity of alpelisib." (PMID 35016012, 2022). "Only surrogate markers of IR were used as opposed to the gold standard method for quantifying insulin sensitivity which is hyperinsulinemia euglycemic glucose clamp method." (PMID 37361870, 2022). "The continued presence of higher endogenous insulin levels after diet reversal possibly implies that diet change alone is not adequate to attenuate HF induced hyperinsulinemia." (PMID 36012550, 2022). "The significant upregulation of IGF-1 in livers of male offspring of obese dams together with hyperinsulinemia at P21, which has been observed in our prior studies, led us to investigate IGF-1 upstream mediators as well as the insulin and IGF-1 downstream signaling pathway in the liver." (PMID 35628414, 2022).